BECN1 (beclin 1)
Diseases named in the same sentence as BECN1 in open-access papers (continued):
Sharing a sentence is not in itself a finding about the gene and the disease.
glioma (continued). "Consistently, fluorescent immunostaining showed that PD-L1 evidently reduced LC3B and Beclin-1 while increased p62 in starved LN229 glioma cells at EBSS-6 h." (PMID 31850228, 2019). "The triptolide treatment significantly augmented the expression levels of LC3B and Beclin-1 and dramatically reduced the expression level of p62 in a dose- and time-dependent manner in the glioma cells." (PMID 31157167, 2019). "Rapamycin, an inhibitor of the mTOR signaling pathway, promoted malignant glioma cell death and sensitized glioma to combined radiotherapy or temozolomide treatment by autophagic activation along with increased expression of Beclin-1, Atg5 and LC3-II45." (PMID 30302016, 2018). "In glioma, reduced tumor cell progression and relapse by knockdown of CDGSH iron sulfur domain 2 (CISD2) was associated with the activation of Beclin 1-mediated autophagy." (PMID 29774126, 2018). "We additionally analyzed the protein expression level of HDAC3, Tip60, ULK1 (Atg1), and Beclin-1 (Atg6) after treatment with N25 in glioma cells." (PMID 29088860, 2017). "Beclin 1 (mammalian homolog of yeast Atg6), an essential autophagy gene, has been found mono-allelically deleted in various cancers including liver, ovarian, breast, prostate, glioma, colon, and brain." (PMID 28915706, 2017). "On the other hand, autophagy inhibition via adding pharmacological inhibitors or silencing Beclin-1/ATG-5 significantly potentiated LY3023414-induced glioma cell apoptosis." (PMID 29228741, 2017). "Recent study indicates that interaction of Beclin-1 with survivin regulates sensitivity of human glioma cells to TRAIL (a death receptor ligand)-induced apoptosis." (PMID 29371939, 2017). "Nevertheless, N25 inhibited HDAC3 and up-regulated the protein expression of Tip60, ULK1 (Atg1), and Beclin-1 (Atg6) after treatment of glioma cells with N25." (PMID 29088860, 2017). "Nevertheless, N25 inhibited HDAC3 and up-regulated the protein expression of Tip60, ULK1, and Beclin-1 in glioma cells." (PMID 29088860, 2017). "In this study, the major novel findings were that miR-129 is a new inducer of autophagy both through mTOR signaling and upregulation of Beclin-1 by targetedly suppressing Notch-1 in glioma cell lines." (PMID 26824182, 2016). "In conclusion, these findings identify a new function for miR-129 as a potent inducer of autophagy through a novel Notch-1/E2F7/Beclin-1 axis in glioma." (PMID 26824182, 2016). "We use immunohistochemical (IHC) staining to evaluate TGF-β1, AEG-1, MAP-LC3, BECN1, E-cadherin and N-cadherin expression in formalin-fixed, paraffin-embedded sections of normal brain and brain tumors with glioma grading." (PMID 26909607, 2016). "Consistent with the result of miR-129 overexpression and Notch-1 inhibition, E2F7 also increased Beclin-1 protein levels and induced autophagy in U87 and U251 glioma cells." (PMID 26824182, 2016). "Of particular interest are recent findings that high-grade gliomas have lower expression of Beclin 1 when compared with low-grade gliomas." (PMID 25726528, 2015). "H2O2 induces autophagy through interference with the beclin-1 and Akt/mTOR signaling pathways, and is regulated by the anti-apoptotic gene Bcl-2 in glioma U251 cells." (PMID 22363680, 2012). "We have reported that inhibition of Beclin 1 increased the caspase activities in glioma cells treated with TRAIL via reducing survivin level." (PMID 22496897, 2012). "In this study, we observed the inhibition of cell viability and overexpression of the Beclin 1 protein in C6 glioma cells after Cas III-ia treatment." (PMID 22540380, 2012). "LC3 and Beclin 1 overexpression were evaluated in C6 glioma cells as indicative of autophagosomal activation." (PMID 22540380, 2012). "The interaction between beclin-1 and Bcl-2 proteins may represent a key molecular switch that controls whether glioma cells undergo survival or death." (PMID 41511337, 2025).
glioma (continued). "The results of this research showed that the usage of the intracellular survival signaling pathway inhibitors PI3K-Akt/PKB-mTOR and Ras-Raf-MEK-ERK in simultaneous application resulted in the formation of Bcl-2 and beclin-1 complexes, which was correlated with induction of apoptosis in glioma cells." (PMID 38067099, 2023). "Therefore, the aim of the present study was to investigate, for the first time, the role of Bcl-2:beclin-1 in “switching” between apoptosis and autophagy in glioma cells using the combined action of LY294002 and sorafenib." (PMID 38067099, 2023). "Expanding knowledge of the central nervous system tumors, such as malignant gliomas, based on the role of the molecular switch, the Bcl-2:beclin-1 complex may be the basis of modern anticancer therapy development." (PMID 38067099, 2023). "High expression of autophagy-related proteins such as BECN1 is more pronounced in high-grade glioma than in low-grade, so BECN1 might be a prognostic marker for glioma patients." (PMID 36072803, 2022). "Basic experiments have shown that Sev can inhibit cell viability in a dose-dependent manner in U87 and U251 glioma cells, increase ROS levels and Fe2+ concentrations, upregulate the expression of transferrin, ferritin, and Beclin-1, and induce glial tumour cell death." (PMID 36313359, 2022). "Furthermore, the expression levels of LC3 and Beclin-1 were also upregulated in the eIF4E-silenced glioma cells (P <0.01)." (PMID 34917504, 2021). "Furthermore, the different therapies increased the expression of LC3 and Beclin-1 in the gliomas (P<0.01)." (PMID 34917504, 2021). "Furthermore, borneol markedly increased the number of autophagosomes in the glioma cells, which coincided with increased expression of beclin-1 and LC3." (PMID 34917504, 2021). "Autophagy is a controversial program that promotes or inhibits cancer cell death, depending on the cellular context, however, reduced spontaneous autophagy activity is shown in glioma cells, with low expression and high cytoplasmic score of the autophagy-related marker Beclin-1." (PMID 33663509, 2021). "In vitro studies showed that the overexpression of p72 RNA helicase in T98G and A172 glioma cells and glioblastoma biopsy samples increased the formation of miR-34-5p and miR-5195-3p, which inhibit the expression of Beclin-1, favoring migration, invasion, and apoptosis in neoplastic cells." (PMID 30486451, 2018). "Besides these pharmacological evidences, our results further showed that silencing Beclin-1/ATG-5 also significantly potentiated LY3023414-induced glioma cell death and apoptosis." (PMID 29228741, 2017). "Indeed, we demonstrated that overexpression of miR-129 or knockdown of Notch-1 not only inhibited mTOR activity but also increased Beclin-1 protein levels in glioma cells." (PMID 26824182, 2016). "In addition, amounts of beclin-1, an upstream modulator of autophagy, in human glioma cells were further analyzed." (PMID 27774504, 2016). "Previous research has shown decreased expression of Beclin-1 in high-grade gliomas." (PMID 26824182, 2016). "Therefore, the aim of this study was to assess, for the first time, the contribution of the formation of the Bcl-2 and beclin-1 complex in the context of the glioma cell elimination through programmed cell death induction using the combined action of LY294002 and sorafenib." (PMID 38067099, 2023). "Notably, the elevated levels of Beclin-1 and LC3 were linked to better survival in glioma patients." (PMID 33525678, 2021). "In vivo repaglinide prominently prolonged the median survival time of mice bearing orthotopic glioma, reducing Bcl-2, Beclin-1 and PD-L1 expression in glioma tissues and indicating that repaglinide may exert its anti-cancer effects via apoptotic, autophagic and immune checkpoint signaling." (PMID 33212778, 2020). "Thus, silencing Beclin-1 or ATG-5 could also efficiently sensitize LY3023414's activity in glioma cells." (PMID 29228741, 2017).
glioma (continued). "In this study, the combination of TMZ and CPUK02 led to an increase in autophagy markers, including LC3-II, p62, and Beclin-1, compared to TMZ alone in U87 human glioma cells." (PMID 41346768, 2026). "The deletion or lower expression of important genes (Beclin-1, FIP200, blood-inducing factor 1 (Bif1), UVRAG, Atg4c and Atg5) is reported in gliomas for autophagosome initiation and elongation." (PMID 33525678, 2021). "Consistent with this, silencing of either mTORC1 or eIF4E significantly decreased the levels of HIF-1α in glioma cells, and increased that of LC3 and Beclin-1." (PMID 34917504, 2021). "MTORC1 knockdown significantly decreased HIF-1α expression in glioma cells (P < 0.01), and increased that of LC3 and Beclin-1 (P <0.01)." (PMID 34917504, 2021). "WP-1006 also promoted the upregulation of the autophagy-related protein Beclin 1 induced by the combination of sorafenib and TMZ in U251 glioma cell lines." (PMID 34277607, 2021). "On the other hand, silencing Beclin-1 significantly decreased the expression of VEGF, MMP2, and HIF-1α in U87-MG glioma cells, leading to a reduction in the length of vasculogenic mimicry (VM) tubes under hypoxic conditions." (PMID 32707662, 2020). "To further confirm that triptolide induces autophagy in glioma cells, we determined the expression of LC3B, p62 and Beclin-1, which are important autophagy-related proteins, using western blotting." (PMID 31157167, 2019). "We have investigated different autophagy markers, such as Atg5, Atg7, Beclin-1, LC3A/B, and p62, from all three GBM cell lines (U-87MG, GL261, and F98), and from C6-glioma and N2a cells." (PMID 30669284, 2019). "Dihydroartemisinin increased Beclin-1 and LC3-B expression levels, induced autophagy in glioma cells, inhibited cell viability, and enhanced the anti-tumor effect of temozolomide." (PMID 27242439, 2016). "To study the role of miR-129- and E2F7-induced autophagy on viability of glioma cells, we performed MTT assay by using 3-MA, Beclin-1 siRNA (sibeclin-1) or Atg5 siRNA (siAtg5) to block autophagic flux, respectively." (PMID 26824182, 2016). "Here, we observed a decrease in Bcl-2 expression in glioma cells subjected to TMZ-Se treatment, indicating that the decrease of Beclin 1 leads to the dissociation of Beclin1 with Bcl-2, thereby promoting the degradation of Bcl-2 and causing apoptosis." (PMID 22496897, 2012). "In 39 glioma cases, we assessed the protein expression of autophagy markers LC3B, SQSTM1/p62, and DRAM by immunohistochemistry (IHC) and the mRNA expression of the autophagy genes PTEN, PI3K, AKT, mTOR, ULK1, ULK2, UVRAG, Beclin 1, and VPS34 using RT-qPCR." (PMID 38203743, 2024). "In addition, the combined use of borneol and TMZ significantly increased the expression levels of Beclin-1 and LC3A/B in glioma tissues compared to those in the untreated controls." (PMID 38188151, 2024). "HSV-1 was found to induce autophagy in glioma cells without a significant increase in the expression of the pro-autophagic protein Beclin-1 and an increase in the phosphorylation of mTOR and Akt." (PMID 37026095, 2023). "THC-induced autophagy was not prevented by knockdown of Beclin-1, suggesting that in contrast to glioma, noncanonical autophagy-mediated apoptosis in response to THC in melanoma." (PMID 35011711, 2022). "In addition, western blotting showed that P7C3 treatment increased the protein levels of Beclin-1 and LC3A/B II, and the ratio of LC3-II/LC3-I was up-regulated, indicating that P7C3 promoted the integrity of autophagy flux in glioma cells." (PMID 34221965, 2021). "Moreover, knockdown of Beclin-1, VPS34, and ATG5 can inhibit autophagy in IR-induced cell death in U87MG, U373MG, and LN229 glioma cells." (PMID 34204169, 2021). "The knockdown of ATG7 and BECN1 could inhibit autophagy and interrupt the effects of TMZ in glioma cells." (PMID 34204169, 2021). "In contrast, Beclin-1 was increased in C6-glioma, but not in N2a cells after Cur and or SCLP treatment." (PMID 30669284, 2019).
glioma (continued). "Consistent with our predictions, Beclin-1 was observed to be upregulated while LC3-I/II and p62 was downregulated evidently (P < 0.05), indicating that Prucaloprid promoted autophagy in glioma cells." (PMID 29866060, 2018). "Vandetanib induces autophagy by inhibiting the PI3K/AKT/mTOR pathway, whereas pharmacologic (chloroquine and 3-MA) or genetic (Beclin-1 and ATG7 knockdown) autophagy inhibition boosts the antineoplastic effect of vandetanib through apoptosis by the mitochondrial pathway in glioma cell lines." (PMID 30486451, 2018). "The interaction of autophagic governor Beclin-1 and survivin could respond to TRAIL in human glioma cells." (PMID 29371939, 2017). "Honokiol treatment increased autophagy markers, Beclin-1 and LC3-II in glioma cells." (PMID 28977840, 2017). "BECN1 or Beclin 1 is an autophagosome initiator that is overexpressed in glioma cells, but not expressed in normal brain neurons or glial cells." (PMID 28977840, 2017). "Although direct glioma-specific evidence linking PLCγ1/PKC-mediated phosphorylation to disruption of the Bcl-2:beclin-1 complex is limited, existing studies demonstrate that PLCγ1-driven Ca2+ flux modulates autophagy-apoptosis balance by influencing beclin-1 availability at the ER membrane." (PMID 41511337, 2025). "However, the expression of mTOR, p-mTOR, ATG5, ATG12 and Beclin-1 in glioma cells was not increased after Co3O4 NPs treatment, which confirmed that Co3O4 NPs did not induce autophagy." (PMID 34683892, 2021). "Finally, by analyzing the relationship of protein levels amongst Bax, Bcl-2, Beclin-1, and the caspase family proteins, it was confirmed that long-term treatment with ING4 can induce parallel pathways of both autophagy and apoptotic cell death in glioma cells." (PMID 30643005, 2019). "As expected, overexpression of ASCL2 caused increased autophagic flux, as evidenced by conversion from LC3‐I to LC3‐II and degradation of SQSTM1 in multiple glioma cells, but did not significantly affect ATG7 and BECN1." (PMID 35882624, 2022).
melanoma (63 papers, 2011 to 2026). A malignant, usually aggressive tumor composed of atypical, neoplastic melanocytes. "Becn1/Beclin1-deficient melanoma cells in the TME expressed high levels of CCL5 via the activation of the MAPK8/JNK-JUN/c-Jun signaling pathway, which boosted the infiltration of functional NK cells into the TME and curtailed tumor progression." (PMID 36300110, 2022). "Activated JNK releases Beclin-1 by phosphorylating Bcl-2 and B-cell lymphoma-extra large (Bcl-XL), thereby activating autophagy and enhancing cellular resistance to apoptosis in melanoma cells." (PMID 40655947, 2025). "AC-1001-H3, a synthetic peptide, induces autophagy through ROS generation and elevates the levels of LC3/LC3-II and Beclin 1 in melanoma cells." (PMID 39371094, 2024). "Physalin A, a steroidal compound of physalis plants, induces autophagy in melanoma A375-S2 cells by upregulating the p38-NF-κB pathway and activating the expression of Beclin 1 and regulating LC3-II/LC3-I proportions." (PMID 39371094, 2024). "For example, Polygonatum odoratum lectin (POL) induced autophagy in A375 human melanoma cells by suppressing miR-1290 levels and enhancing Beclin-1 expression." (PMID 39125630, 2024). "Silencing of CCL5 in Beclin 1 KO melanoma cells reverts the ability of autophagy inhibition to regulate tumor regression and NK infiltration." (PMID 38071322, 2023). "Recently, genetically targeting the autophagy-related gene Becn1/Beclin1 in B16-F10 malignant melanoma cells increases the infiltration of functional NK cells into melanoma tumors and inhibits their growth." (PMID 36003368, 2022). "Beclin-1 targeting for inhibiting autophagy in melanoma cells has been shown to result in recruitment of natural killer (NK) cells in the tumor bed via C-C motif chemokine ligand 5 (CCL5) induction, thereby leading to tumor growth suppression." (PMID 33809137, 2021). "Since our previously published and current data show decreased expression of three of the core ATGs (ATG5, ATG7 and Beclin-1) in melanoma, we decided to study the impact of NRF1 and NFE2L2 on the expression of these ATGs." (PMID 34458153, 2021). "We have recently shown that several proteins involved in the autophagic process; ATG5, Beclin-1 and BIF-1 are reduced in melanoma patients and that reduction of ATG5 and BIF-1 is associated with a less favourable patients’ outcome." (PMID 34458153, 2021). "We have previously reported that genetic targeting of Becn1 in melanoma cells prevents the degradation of Natural killer (NK)-derived Granzyme B and enhances melanoma susceptibility to NK-mediated killing." (PMID 33718194, 2021). "Aberrant expression autophagic genes have been documented as observed in clinical samples, and LC3-II expression and beclin-1 in melanoma patient parallels disease stage and progression." (PMID 34475961, 2021). "The immunohistochemical expression of Beclin-1 has been detected, in fact, in about 100% of benign nevi and 86.4% of dysplastic nevi, decreasing to 54.3% in primary melanomas and up to 26.7% in melanoma metastases." (PMID 33330070, 2020). "From this, the protein data showed that FKB treatment reduced the expressions of Beclin-1 and Bcl-2 proteins dose-dependently and led to autophagy in melanoma cells." (PMID 33053749, 2020). "It has also been demonstrated, however, that targeting Beclin-1 in melanoma cells increased the infiltration of natural killer (NK) cells into melanoma tumors that was dependent on increased expression of the C-C motif chemokine ligand 5 (CCL5)." (PMID 32340261, 2020).